TERC (telomerase RNA component)
Diseases named in the same sentence as TERC in open-access papers (continued):
Sharing a sentence is not in itself a finding about the gene and the disease.
cervical adenocarcinoma (1 paper, 2006). An adenocarcinoma arising from the cervical epithelium. "This is the first study that reports the consistent gain of the human telomerase gene TERC in cervical adenocarcinomas." (PMID 16847471, 2006). "We then used FISH with a custom-designed probe panel that includes the human telomerase gene (TERC) to assess the potential of this genetic marker to ameliorate the morphological diagnosis of cervical adenocarcinomas." (PMID 16847471, 2006). "The level of genomic amplification of the human telomerase gene TERC, which maps to chromosome band 3q26, was determined in primary cervical adenocarcinomas." (PMID 16847471, 2006). "In our study, we analysed a series of 12 primary cervical adenocarcinomas for gain or amplification of the human telomerase gene TERC, which maps to chromosome band 3q26." (PMID 16847471, 2006). "Twelve cervical adenocarcinomas were evaluated for copy number changes of the TERC locus at chromosomal band 3q26 using interphase FISH." (PMID 16847471, 2006). "As the results of the current study indicate, TERC appears to play a similar important role in the carcinogenesis of cervical adenocarcinomas." (PMID 16847471, 2006). "Amplification of the human telomerase gene TERC is a consistent aberration in cervical adenocarcinomas." (PMID 16847471, 2006). "Fluorescence in situ hybridisation analyses of precursor lesions, that is, adenocarcinomas in situ and dysplasias will be the next step to verify the potential of TERC as a marker of early detection and progression in cervical adenocarcinomas." (PMID 16847471, 2006). "Interphase nuclei prepared from archival material of 12 primary cervical adenocarcinomas, eight of which were human papillomavirus positive, were hybridised with a triple colour probe set specific for centromeres of chromosomes 3 and 7 and the TERC gene." (PMID 16847471, 2006). "Using a genomic probe for the TERC gene on chromosome band 3q26 in combination with two centromere-specific probes (CEP3 and CEP7), we showed high copy numbers of this locus in cervical adenocarcinomas." (PMID 16847471, 2006).
cervical dysplasia (1 paper, 2014). "TERC is the most frequently observed amplified oncogene in cervical precancerous lesions and linked to high-grade cervical dysplasia and cancer." (PMID 24410919, 2014).
chronic myeloid leukemia (1 paper, 2017). "Comparable thresholds of >2.31 and >2.5 were used in studies on TERC gene amplification in chronic myeloid leukemia and EGFR copy number in metastatic lung cancer." (PMID 28415661, 2017).
clear cell renal cell carcinoma (1 paper, 2025). "However, genomic analyses in clear cell renal cell carcinoma (CCRCC) have revealed that female patients with elevated DKC1 expression also exhibit increased TERC levels, a pattern associated with reduced therapeutic response and shorter progression-free survival." (PMID 40642018, 2025).
cystic fibrosis (1 paper, 2023). Autosomal recessive disorder caused by pathogenic variants in the CFTR gene (cystic fibrosis transmembrane conductance regulator), which encodes a chloride and bicarbonate channel expressed in epithelial cells, and follow the diagnosis criteria. "Strain C3 from Australia was isolated from a patient with cystic fibrosis and presented clpK1 and terC genes, while environmental strains from the United Kingdom carried terC and traT genes." (PMID 38003800, 2023).
histiocytic sarcoma (1 paper, 2016). An aggressive malignant neoplasm with a poor response to therapy, usually presenting as stage III/IV disease. "Histiocytic sarcoma was reported to be the most frequent tumor lesion in C57Bl/6 mice, including p66SHC−/− and TERC−/− models." (PMID 26968134, 2016).
liver cirrhosis (1 paper, 2020). "The authors analyzed TERT and TERC mutations in buccal mucosa tissue and peripheral blood of patients with liver cirrhosis and compared them with healthy non-cirrhotic controls." (PMID 32722302, 2020).
lymph node metastasis (1 paper, 2017).
macrocytic anemia (1 paper, 2009). Anemia that is characterized by increased red blood cell volume. "The proband's thirty-two year-old son (Subject B-III-7) is heterozygous for the TERC deletion; he had mild macrocytic anemia during a routine medical visit." (PMID 19936245, 2009).
mental disorder (1 paper, 2020). A disease that has its basis in the disruption of mental process. "The expression level of TFRC is associated with mental disorders, suggesting that TERC could use as a molecular target for studying the pathogenesis of DEP." (PMID 32457667, 2020).
myeloproliferative disorder (1 paper, 2018). A clonal hematopoietic stem cell disorder, characterized by proliferation in the bone marrow of one or more of the myeloid (i.e., granulocytic, erythroid, megakaryocytic, and mast cell) lineages. "Only one compound, imetelstat (GRN163L), an oligonucleotide that binds to the RNA subunit of telomerase TERC, has shown efficacy in myeloproliferative disorders, but has displayed limited activity in solid tumors." (PMID 29695835, 2018).
neuroblastoma (1 paper, 2024). Neuroblastoma (NB) is the most common solid, extracranial childhood tumor. "All neuroblastoma cell lines in this study expressed TERC, with long telomere cell lines tending toward lower expression compared with short telomere cell lines." (PMID 38837897, 2024).
oral cancer (1 paper, 2016). "To further confirm that FXR1 is a key regulator of senescence in these oral cancer cell lines and it does so by modulation p21 and TERC RNA, we set up the following experiment." (PMID 27606879, 2016). "Taken together, these data indicate that FXR1-regulated repression of senescence involves both down-regulation of p21 and up-regulation of TERC in oral cancer cells." (PMID 27606879, 2016). "P21 is overexpressed more than 18-fold (p<0.05) and TERC is significantly (p<0.05) downregulated in oral cancer cells." (PMID 27606879, 2016). "An equally steady decrease of both TERC and FXR1 is observed under FXR1 depleted oral cancer cells." (PMID 27606879, 2016).
ovarian carcinoma (1 paper, 2019). A malignant neoplasm originating from the surface ovarian epithelium. "A component of the telomerase enzyme complex, TERC is implicated in maintaining telomere length and therefore genetic susceptibility to aging related diseases, such as ovarian cancer." (PMID 31379598, 2019). "Our ranking and literature search on the biological role of TERC suggests it may be a new lncRNA that could be related to ovarian cancer." (PMID 31379598, 2019).
Pancytopenia (1 paper, 2009). An abnormal reduction in numbers of all blood cell types (red blood cells, white blood cells, and platelets). "We now screened his brother (Subject C-III-3), with a long history of mild pancytopenia and elevated liver enzymes, and he also tested positive for the TERC deletion." (PMID 19936245, 2009).
papilloma (1 paper, 2021). A benign epithelial neoplasm that projects above the surrounding epithelial surface and consists of villous or arborescent outgrowths of fibrovascular stroma. "However, when the same TPA treatment was applied to K5-TERT/TERC−/− mice, the number of papillomas developed were lower than those observed in wild-type and TERC−/− mice." (PMID 33599797, 2021).
Pituitary Adenomas (1 paper, 2022). "The findings in our study reveal that TERC rs35073794 is strongly associated with the development of pituitary adenoma." (PMID 35892421, 2022). "TEP1, TERC, and TERT genes single nucleotide polymorphisms were analyzed to evaluate the associations with pituitary adenoma activity, invasiveness, and relapse." (PMID 35892421, 2022). "Thus, this study aimed to determine the relationship between the molecular markers of telomerase complex (TERC rs12696304, rs35073794, TEP1 rs1713418, rs1760904, and TERT rs2736098, rs401681) and the relative leukocyte telomeres length with the development of pituitary adenoma." (PMID 35892421, 2022).
pneumonia (1 paper, 2021). An acute, acute and chronic, or chronic inflammation focally or diffusely affecting the lung parenchyma, caused by an infection in one or both of the lungs (by bacteria, viruses, fungi, or mycoplasma.). "We previously reported a strong association between the ter operon and Kp infection (pneumonia and bacteremia) in Kp colonized patients, yet also found that terC is dispensable in a murine model of pneumonia." (PMID 33930099, 2021).
pulmonary disease (1 paper, 2011). "A similar spectrum of disease severity can be observed in families with TERC mutations, although these appear more likely to present with haematological abnormalities than pulmonary disease." (PMID 21931702, 2011).
silicosis (1 paper, 2025). Silicosis is a respiratory disease caused by breathing in (inhaling) silica dust. "Among the patients with silicosis, 8.3% had TERT variants and no TERC variants were detected." (PMID 39813504, 2025).
skin atrophy (1 paper, 2019). The degeneration and thinning of the epidermis and dermis. "Patients with mutations in the telomerase component (eg, Dyskerin, TERT, TERC) are frequently accompanied by symptoms of abnormal epidermis, such as hyperpigmentation, premature skin degradation, hair follicle shedding, skin atrophy, and dry skin." (PMID 31518356, 2019). "Moreover, patients with the mutation of telomerase components (e.g. Dyskerin, TERT, TERC) exhibit telomere shortening and skin atrophy." (PMID 31518356, 2019).
spinal cord injury (1 paper, 2023). Penetrating and non-penetrating injuries to the spinal cord resulting from traumatic external forces (e.g., WOUNDS, GUNSHOT; WHIPLASH INJURIES; etc.). "This study investigated the function of telomerase RNA component (TERC) in spinal cord injury (SCI)." (PMID 36742154, 2023).
urinary tract infection (1 paper, 2023). "Additionally, this finding that TerC is a fitness factor during a urinary tract infection implies a conserved mechanism of fitness enhancement in the gut and bladder that is dispensable in the lung and blood." (PMID 36651775, 2023). "Here, we demonstrate a novel role for TerC as a fitness factor during a urinary tract infection." (PMID 36651775, 2023).
Uterine leiomyoma (1 paper, 2020). The presence of a leiomyoma of the uterus. "Although the effect of uterine leiomyoma risk allele on telomere length is inverted between TERT and TERC loci, the relationship between telomere length and neoplastic disease risk is contradictory." (PMID 31988393, 2020).
cancer (83 papers, 2011 to 2025). A tumor composed of atypical neoplastic, often pleomorphic cells that invade other tissues. "The corresponding gene candidates included the telomerase RNA component (TERC), which had previously been shown to be associated with leukocyte telomere length and the risk of diverse cancer types." (PMID 38308367, 2024). "Oligonucleotides, antisense-oligodeoxynucleotides and siRNAs, that interfere with TERT mRNA and TERC itself, were shown to rapidly inhibit cancer cell growth and increase susceptibility to treatment." (PMID 37189709, 2023). "On the other hand, overexpression of TERT and TERC are associated with cancer progression as they enhance cell proliferation." (PMID 33599797, 2021). "In cancer, TERC is dysregulated by various mechanisms such as mutations and copy number increase that is generally correlated with cell proliferation and disease progression." (PMID 33599797, 2021). "It was previously discovered that TERC is implicated in angiogenesis, metastasis and proliferation of cancer cells by regulating the global gene expression." (PMID 31294790, 2019). "Variants and copy number changes at the TERC locus have been associated with cancer risk and progression." (PMID 31808800, 2019). "Recent studies indicated that rs10936599 in TERC was associated with telomere length and with an increased risk of cancers, but the conclusions were inconsistent." (PMID 29299136, 2017). "A number of studies have reported that single nucleotide polymorphisms (SNPs) of TERT and TERC gene are associated with a significantly higher susceptibility to multiple types of cancers." (PMID 29299136, 2017). "TERC is linked to telomerase activity, which is up-regulated in stem cells, cancer cells and proliferating lymphocytes." (PMID 27553844, 2016). "Telomeric repeat-containing RNAs (TERRA) and telomerase RNA component (TERC) regulate telomerase activity (TA) and thereby contribute to telomere homeostasis by influencing telomere length (TL) and the cell immortality hallmark of cancer cells." (PMID 39222177, 2025). "Numerous studies have revealed an intimate association between the variants of the TERT or TERC gene and susceptibility to cancer, aging-associated disorders and many other pathological conditions, however, their relationship with primary GN/CKD/ESRD has never been explored." (PMID 32366311, 2020). "Cancer incidence is higher among patients with TERC and TERT mutations, significantly so compared to the TINF2 group (P-value = 0.003 and 0.011, respectively); this may well reflect the fact that they are generally an older patient group." (PMID 21931702, 2011). "Thus, our study aims to investigate the association of HOTAIR rs920778, MIR155HG rs1893650, TERC rs10936599, miR-155 rs767649, miR-196a2 rs11614913 and miR-146a rs2910164 genetic variations with the cancer risk, progression, and progression-free survival of PTC patients." (PMID 38339237, 2024). "Understanding the biological functions of TERC is crucial for unraveling the mechanisms behind telomere maintenance and their implications in aging, cancer, and other age-related diseases." (PMID 40696438, 2025). "Telomerase activity is normally limited to stem, germ and the majority of cancer cells, but TERC is expressed in a majority of somatic cells where it is expressed constitutively." (PMID 38721690, 2025). "Conversely, silencing NOP10 significantly reduces the expression of SNORA65, SNORA7A, and SNORA7B, as well as suppressing cancer cell proliferation and migration, ultimately decreasing TERC levels." (PMID 39871386, 2025). "Specifically, two loci—5p15.33 of TERT and 3q26.3 of TERC—are observed to be the most common amplifications within cancer types." (PMID 39858038, 2025).
cancer (continued). "Therapeutics in the pipeline targeting TERC, such as a possible gene therapy, has been postulated to prevent cancer." (PMID 39858595, 2025). "More and more evidence suggests that TERC plays an important role in telomere maintenance and other functions in human cancer." (PMID 39668827, 2024). "Through a variety of processes, including amplification of the hTR-encoding genes TERC and TERT, telomerase activity increases in cancer." (PMID 39239547, 2024). "The design of TERC-specific ASOs therefore inhibit telomerase activity and has shown promise in preclinical studies in various cancers, including CRC." (PMID 39273409, 2024). "Dyskerin (DKC1), encoded by the DKC1 gene on X chromosome, is a telomerase co-factor stabilizing telomerase RNA component (TERC), whereas telomerase plays key roles in cancer development and progression." (PMID 37434223, 2023). "Dyskerin (DKC1), encoded by the DKC1 gene within Xq28, is a telomerase co-factor stabilizing telomerase RNA component (TERC) and overexpressed in various cancers." (PMID 37434223, 2023). "Upregulation of TERC expression was found in 15/21 of cancer types, while a significant reduction was documented in THCA." (PMID 36239411, 2023). "Increased TERC expression not only enhances telomerase activity to lengthen telomeres, but also promotes cancer aggressiveness independently of the canonical telomerase function." (PMID 37434223, 2023). "This implicates TERC as an oncogenic lncRNA that sponges tumour-suppressing miRNAs, promoting cancer progression." (PMID 37754243, 2023). "TERT expression is accurately regulated in various cells in order to avoid cancer cell transformation, whereas TERC is constitutively expressed in mammalian cells." (PMID 37189709, 2023). "DKC1, RUVBL1, NHP2, and TERC expression was also inversely correlated with DNA methylation in most cancer types." (PMID 36239411, 2023). "From a general point of view, our findings contribute to the basic knowledge of the cellular and extracellular forms of TERRA and TERC produced by cultured cancer cell lines and those detectable in HCC tissues and in the plasma of HCC patients." (PMID 35682861, 2022). "It is noteworthy that sustained proliferation, glycolysis, and de-differentiation are markers of stemness, thus suggesting a specific role for TERC in stem and cancer cells." (PMID 36499514, 2022). "TERC is expressed in all telomerase positive cells, including human stem cells and most cancer cells." (PMID 31294790, 2019). "Alternative applications within the scope of gene therapy exploiting constitutive activation of TERT in cancer utilize silencing or inhibition of TERT or TERC activity." (PMID 31035374, 2019). "This site in TERC needed to be further investigated to research correlations between rs35073794 and cancers." (PMID 29100352, 2017). "One micrometer SMA exposure for up to 2 weeks induced significantly (P < .05) decreased expression level of TERT and TERC transcripts in each cancer cell line." (PMID 30460075, 2017). "It is reported that genetic variations in telomere length related-genes TERT and TERC are involved in the many types of cancers." (PMID 29100352, 2017). "Other therapeutic strategies have sought to exploit the active promoter-driven expression of TERT or TERC in cancer to express cytotoxic agents in target cells." (PMID 27240403, 2016). "NTR produced by TERT/TERC active cancer cells then converts the pro-drug CB1954 into active cytotoxic 2- and 4-hydroxylamino derivatives that form DNA crosslinks via an N-acetoxy intermediate." (PMID 27240403, 2016). "The percentage of the counted cancer cells with 3-4 copies per cell of TERC was more than 90%, and the percentage of the counted cancer cells with 3-4 copies per cell of CLDN1 was more than 80%." (PMID 27974683, 2016).